CAV1 (caveolin 1)
Diseases named in the same sentence as CAV1 in open-access papers (continued):
Sharing a sentence is not in itself a finding about the gene and the disease.
tumor (continued). "In the present study, we have examined the cav-1 mRNA expression in 136 lung TT and matched tumor-free tissues (TF) using real-time PCR analysis and the protein expression in 20 paired lung TT and TF by Western blot analysis." (PMID 22200856, 2012). "A number of biomarkers identified here are consistent with those reported in the literature in terms of their altered gene expressions in tumor tissues, including caveolin 1, cyclin B1, 14-3-3zeta, Stat5, activated p38, and IGFBP2." (PMID 22348039, 2012). "We confirmed that consistent with mRNA, Cav-1 protein was expressed in the CD133+ tumor cells by Western blot analysis." (PMID 22995409, 2012). "In several in vitro studies, cav-1 was down-regulated in tumor cells isolated from the breast, cervix, lung and ovary, and oncogenic transformation of cells was associated with a reduction in cav-1 expression." (PMID 22200856, 2012). "Cav-1 has been shown in in vitro studies to be down-regulated in various tumor cells including NSCLC." (PMID 22200856, 2012). "Some of the clinical studies also seem to support the positive role of Cav-1 in tumor-induced angiogenesis (in particular studies showing a positive correlation between Cav-1 expressions), tumor microvascular density, and often shorter survival time." (PMID 26605130, 2012). "Taken together, the results of these clinical studies support pro-angiogenic role of Cav-1 expressed either in tumor endothelial cells or tumor cells themselves." (PMID 26605130, 2012). "In human cancers, CAV1 expression is often lost, indicating that CAV1 possesses tumor suppressor capabilities." (PMID 23272165, 2012). "Real-time PCR and Western blot assays were performed to detect cav-1 mRNA and protein levels in tumor tissues (TT) and matched tumor-free tissues (TF)." (PMID 22200856, 2012). "CAV1 expression was detected in the tumor cell cytoplasm of 242 (83.7%) and the tumor cell membrane of 232 (80.3%) patients with clear cell RCC." (PMID 22152020, 2011). "Caveolin-1 acts as a tumor suppressor in the early stages of cancer, but in late stages it promotes metastasis, multidrug resistance, and portends poor prognosis." (PMID 21660237, 2011). "Multivariable Cox regression analysis identified an elevated CAV1 staining value in the tumor cytoplasm as an independent predictor of tumor specific survival." (PMID 22152020, 2011). "Over expression of caveolin-1 in the tumour cell cytoplasm predicts a poor prognosis of patients with clear cell RCC." (PMID 22152020, 2011). "CAV1 has been shown to possess an ambiguous role in cancer and to act both as a tumor suppressor or promoter." (PMID 21471610, 2011). "Genetic evidence supporting the role of CAV1 as a tumor suppressor has emerged from gene mapping studies, which revealed that the human CAV-1 gene maps to the long arm of human chromosome 7 (7q31.1)." (PMID 22152020, 2011). "Association of different patient and tumor specific characteristics with CAV1 protein expression in the tumor cytoplasm." (PMID 22152020, 2011). "The effect of CAV1 on tumor phenotype seems to be very heterogeneous and strongly dependent on the molecular partners interacting with this protein." (PMID 21471610, 2011). "Endothelial cells of dermal lymphatics containing tumor emboli that stained strongly for caveolin-1, consistent with the known high levels of caveolae in endothelial cells." (PMID 22093547, 2011). "In the recent years it has been relatively well agreed that depending on tumor type, CAV1 can have either tumor suppressor or oncogenic effects on a cell." (PMID 21471610, 2011). "Caveolin-1, also known as a tumor-suppressor factor, interacts with a number of transducing molecules that reside in or are recruited to caveolae, and it inhibits cell proliferative pathways." (PMID 21660237, 2011).
tumor (continued). "Kaplan-Meier analysis disclosed significant differences in 5-year overall (51.4 vs. 75.2%, p = 0.001) and tumor specific survival (55.3 vs. 80.1%, p = 0.001) for patients with higher and lower than average cytoplasmic CAV1 expression levels, respectively." (PMID 22152020, 2011). "In support of this view, it has been shown that the caveolin-1 re-expression in tumor cells inhibited MMP activation and function thereby preventing cell migration." (PMID 21660237, 2011). "CAV1 protein expression in the tumor cell cytoplasm and cell membrane correlated moderately but significantly (r = 0.52, p < 0.001, Pearson)." (PMID 22152020, 2011). "Based on its location at chromosome 7 (7q31.1), which is frequently deleted in human malignancies, Cav-1 is believed to be a tumor suppressor." (PMID 20700465, 2010). "Nevertheless, there is evidence in tumor cells that Cav1 and Cav2 are up-regulated by PPARγ in human carcinoma cells; annexin II is up-regulated by PPARγ agonists in 3T3-L1 cells and Cav1 is suppressed by Ras-p42 MAP kinase and PKA." (PMID 20574519, 2010). "In contrast, xenografts from cells stably expressing CAV1 or CAVM2 were significantly smaller with an average tumor size of 325 ± 10 mm3 and 340 ± 13.4 mm3." (PMID 19321006, 2009). "The caveolin-1 expression was found significantly higher in tumor cells than its peritumoral cirrhotic tissues in HCC samples (p < 0.001)." (PMID 19239691, 2009). "The assay we developed also included a tumor marker (caveolin-1) which allows the preferential detection of tumor-secreted exosomes." (PMID 19381331, 2009). "Thishypercellularity can be correlated with the excessive proliferation of MEFsderived from caveolin-1 null mice that is observed in cell culture models andis consistent with data proposing caveolin-1 as a tumor suppressor." (PMID 20157570, 2009). "It previously has been shown that regulation of Cav-1 plays a central role in the complex cellular changes leading to metastasis via epithelial-to-mesenchymal transition in human tumor cells overexpressing EGFR." (PMID 19239691, 2009). "This opens new ways to use Cav-1 as a marker of tumor progression, as well as for the design of therapeutic approaches aiming to block its cellular functions." (PMID 19239691, 2009). "Further in vitro studies revealed that Cav-1 protein can directly interact with integrin β1 and Src, thus disrupting integrin β1/Src-mediated tumour cell growth, invasion, and survival during metastasis." (PMID 19002186, 2008). "Nevertheless, the composite covariates of caveolin-1 and activated AKT/mTOR components serve as linked molecular signatures that clearly identify localised tumours, which have high invasive capacity and an increased metastatic potential." (PMID 18283322, 2008). "Specifically, caveolin-1 triggers signalling events that are consistent with a role both as a tumour suppressor or as a tumour promotor." (PMID 18400052, 2008). "Caveolin-1 was mainly located at the membrane and in the cytoplasm of the tumour cells as well as in the endothelial cells." (PMID 19002186, 2008). "Among 30 PD, 67 MD, and 17 WD tumour samples, the expression of Cav-1 was lowest in the PD category (P<0.0001) (right)." (PMID 19002186, 2008). "The caveolin-1/pAKT composite covariate strongly correlated with tumour grade (P=0.044), tumour size (P=0.008) and vascular invasion (P=0.001)." (PMID 18283322, 2008). "Quantitative analysis of Tu-1, LNM-1, and Tu-2 samples revealed that expression of Cav-1 was significantly downregulated in LNM-1 compared with primary tumours (median WI=82.5 for LNM-1 vs median WI=127 for Tu-1 and 140 for Tu-2, P<0.0001)." (PMID 19002186, 2008). "Studies supporting Cav-1 as a negative regulator of tumour progression have been thoroughly reviewed." (PMID 19002186, 2008). "We interpret from this that patients with localised RCC whose tumours are positive for both caveolin-1 and pAKT are likely to have more aggressive and vasoinvasive disease." (PMID 18283322, 2008).
tumor (continued). "Tumours that coexpressed caveolin-1 and activated mTOR components were more likely to be larger, higher grade and to show vascular invasion." (PMID 18283322, 2008). "Here, in an extended patient cohort (174 patients), we show that caveolin-1 expression strongly correlates with tumour size, tumour grade and the presence of vascular invasion." (PMID 18283322, 2008). "In the past 10–15 years, a large amount of data have accumulated associating changes in caveolin with the process of cell transformation and indicating that caveolin-1 functions as a tumour suppressor." (PMID 18400052, 2008). "Increased expression levels of caveolin-1 strongly correlated with tumour grade (P=0.019), vascular invasion (P=0.001) and tumour size (P=0.003)." (PMID 18283322, 2008). "An important question that remains to be resolved is how, if at all, these molecular events relate to suppression of caveolin-1 expression observed early in tumour development or re-expression of caveolin-1 detected at later stages." (PMID 18400052, 2008). "The only significant relation between CAV1 expression and poor outcome was observed in the low tumour grade cohort of patients (Grade 1), where positive expression of CAV1 was associated with shorter DFS (P=0.013)." (PMID 18612310, 2008). "In tumour tissues, a typical peripheral staining pattern was frequently observed in which Cav-1 immunoreactivity was seen in only the outer cell layer of the nest, whereas the rest of the keratinocytes and necrotic cells were negative." (PMID 19002186, 2008). "Support for this notion is in part provided by other clinical studies that show that the overexpression of caveolin-1 is correlated with increased microvessel density within tumours not only of the kidney but also the prostate." (PMID 18283322, 2008). "In the following paragraphs, evidence indicating that caveolin-1 displays traits consistent with a role as a tumour suppressor and/or tumour promotor is summarized." (PMID 18400052, 2008). "To address this, we examined the coexpression of caveolin-1 and phosphorylated mTOR (pmTOR) pathway components in tumour tissue from 174 RCC patients presenting with localised disease." (PMID 18283322, 2008). "An association between the expression of caveolin-1 and AKT has been previously reported in clinical tumours of the colon." (PMID 18283322, 2008). "Expression of Cav-1 was inversely associated with metastasis of HNSCC, but positively associated with tumour differentiation." (PMID 19002186, 2008). "The time to relapse was also substantially shortened for patients whose tumours coexpressed caveolin-1 and pS6, with a survival of 1.45 years compared with 5.96 years (P<0.0001)." (PMID 18283322, 2008). "The contribution of Caveolin-1 to carcinogenesis and tumour progression has been intensively evaluated." (PMID 17915016, 2007). "Several studies have investigated caveolin-1 down-regulation in cancer, and hence provided further evidence that it acts as a tumour suppressor." (PMID 18949068, 2007). "Our combined results with p27 and caveolin-1 demonstrate a potential PPAR dependent molecular mechanism for the inhibition of tumor growth by CDIM9." (PMID 17764562, 2007). "So far, most of the evidence for this theory relates to caveolae, and, as we will describe, caveolin-1 has been identified as a possible tumour suppressor gene." (PMID 18949068, 2007). "Different groups found caveolin-1 to be down-regulated in tumours derived from the ovary, breast and colon." (PMID 18949068, 2007). "The mechanism underlying tumor growth inhibition by CDIM9 probably involves PPAR-γ activation and upregulation of the cell cycle regulating genes p27 and caveolin-1." (PMID 17764562, 2007). "In some tumours and tumour cell lines, it has been found that either caveolin-1 levels are unchanged compared to normal cells, or they are actually increased." (PMID 18949068, 2007).
tumor (continued). "Positive caveolin-1 expression was correlated with tumour diameter (P=0.0079), histopathologic grade (P=0.0272) and poor prognosis (P=0.0008)." (PMID 12402154, 2002). "Our findings reveal that key CAV1 phosphosites modulate oncogenic signaling, cytoskeletal remodeling, and membrane organization, providing novel insights into CAV1-mediated cellular functions and its context-dependent role in tumor progression." (PMID 42196307, 2026). "Additionally, opposing effects of Cav-1 and Cav-2 have been noted in tumor-induced angiogenesis, suggesting that Cav-2 is not only a partner of Cav-1 in caveolae formation but also assists in fine-tuning basic cellular processes in a counterbalancing manner." (PMID 40041164, 2025). "CAV1 functions as a scaffolding molecule for several signaling molecules, including epidermal growth factor receptor (EGFR), and its overexpression and tumor‐promoting activity are associated with metastasis and poor prognosis in bladder, lung, cervical, and other cancers." (PMID 40419438, 2025). "In line with the observed suppressing effect of BRAT1 on its expression, Cav-1 has been described to function as a putative tumor suppressor in GBM, further highlighting the notion of targeting BRAT1 to inhibit the migrative and invasive capacity of this tumor." (PMID 39833546, 2025). "Additionally, spatial transcriptomic analysis identified heterogeneous overexpression of core taurine metabolic genes (e.g., SLC27A5, CAV1) in tumor core regions, which were significantly co-localized with fibroblasts and macrophages." (PMID 40630945, 2025). "Gene therapy, using viral vectors or CRISPR/Cas9-based systems, may restore Cav-1 expression in tumor-suppressive contexts, while RNA-based therapies (e.g., siRNA or miRNA) could inhibit Cav-1 expression in cancers where it functions as an oncogene." (PMID 40963741, 2025). "CAV1 is known for its tumor-suppressive properties and roles in regulating signaling pathways." (PMID 40898538, 2025). "Conversely, in cancers where Cav-1 is upregulated, inhibiting Cav1 could suppress tumor proliferation, invasiveness, and angiogenesis." (PMID 40963741, 2025). "Therefore, through multiplex immunofluorescence staining of tumor tissue sections derived from subcutaneously implanted Pan02 tumor cells in mice, we determined that CAV1 is highly enriched in CK18+ epithelial cells." (PMID 40180904, 2025). "Autophagy activation leads to the degradation of Cav-1 in tumor stromal cells." (PMID 41030451, 2025). "The tumor-suppressive role of Cav1 can be mediated through several mechanisms, including the inhibition of proliferative signaling pathways, suppression of oncogenic signaling, activation of pro-apoptotic pathways and senescence, and regulation of metastasis and invasion." (PMID 40963741, 2025). "Notably, caveolin-1 has been shown to function as both an antiapoptotic and a proapoptotic protein, acting as a tumor promoter in some contexts and a tumor inhibitor in others." (PMID 41312360, 2025). "CAV1, a scaffolding protein crucial for the formation of caveolae, is involved in processes like endocytosis and receptor internalization, exhibiting both tumour-suppressive and tumour-promoting properties." (PMID 39780187, 2025). "For instance, sc-seq has uncovered malignant cell subclusters enriched in genes associated with histone deacetylase (HDAC) inhibitor response (ATF3, CAV1), inflammation (LXN, PGM1), and hypoxia-linked tumor metastasis (WSB1), highlighting their importance in tumor progression." (PMID 41450739, 2025). "Multiplex immunofluorescence staining validated the expression of CAV1 on tumor cells." (PMID 40180904, 2025). "In addition to carrying the Braf gene, chromosome 6 carries several genes that are highly expressed in the LNM and tumor populations (Aqp1, Col1a2, Cav1, Cav2, Ptn, RaRes2, Fkbp9, Actg2, Ybx3, Mgp, Sox5, Kcna1, and Ptms)." (PMID 40571713, 2025).
tumor (continued). "On the other hand, as demonstrated in functional enrichment and correlation analyses, CAV1 may alter the immune cell types in the tumor microenvironment through modulation of the TGF-β signaling pathway." (PMID 40180904, 2025). "High levels of caveolin-1 inhibit mitochondrial function and suppress tumor activity." (PMID 41312360, 2025). "Tumor-derived Cav-1 has been shown to promote pre-metastatic niche formation and lung metastasis in BC, and BC exosomes contribute to pre-metastatic niche formation and promote bone metastasis of tumor cells." (PMID 40732251, 2025). "Cav1’s role in stromal crosstalk suggests that its inhibition could disrupt the supportive tumor niche by reducing fibroblast activation, angiogenesis and immune evasion." (PMID 40963741, 2025). "Immunohistochemical staining for DNM2 and CAV1 was performed on resected primary tumor specimens from 80 OSCC patients, and the individual expressions and combined expression status of these proteins were analyzed in relation to clinicopathological factors and prognosis." (PMID 40419438, 2025). "Interestingly, knockdown of CAV1 in cancer cells resulted in attenuated tumour growth, decreased proliferation, and impaired migration and invasion, suggesting a tumour-promoting role of CAV1 in cancer cells." (PMID 39780187, 2025). "Additionally, we identify CAV1 as a direct target of the tumour suppressor miRNA, miR-7-5p, and this regulatory axis is conserved in clinical HCC samples." (PMID 40715090, 2025). "When CAV1 function is disrupted, estrogen signaling may be impaired, potentially resulting in abnormal transcription and promoting tumor-like processes." (PMID 41303617, 2025). "Tumor-derived CAV1 promotes pre-metastatic niche formation and lung metastasis in BC." (PMID 40547857, 2025). "Therefore, the development of inhibitors targeting ILK, talin and cav-1 will provide new breakthroughs in the regulation of focal adhesion dynamics and related tumour therapies." (PMID 40045379, 2025). "The correlation between CAV1 and ketogenic metabolism in tumor cells requires further study." (PMID 40180904, 2025). "Downregulated were the critical genes CAV1, VWF, and DCN, suggesting loss of tumour-suppressive functions, and upregulated were SCGB2A1, CLDN4, and immune-related genes CCL3 and GZMB, promoting tumour growth and immune evasion." (PMID 41312167, 2025). "Additionally, Caveolin-1 positively correlates with markers of tumor migration, enhances tumor cell resistance to therapy, and maintains stemness." (PMID 39598347, 2024). "Cav1 suppresses tumor formation via regulation of contractile tension in epithelia." (PMID 38397421, 2024). "The tumor promoter role of CAV1 is now well-established in PCa." (PMID 39339236, 2024). "Furthermore, immunohistochemistry (IHC) analysis on tumor samples showed that the staining for Cav-1, a CHO-binding protein, and pAkt1 was completely absent in lovastatin-treated tumors compared to PBS-treated tumors." (PMID 39706565, 2024). "Furthermore, downregulation of CAV1 promotes ferroptosis in cancer cells and inhibits tumor development." (PMID 38313306, 2024). "Seemingly, CAV1 is involved in the regulation of the switch between glucose dependent mitochondrial respiration and aerobic glycolysis and lipid-dependent energy metabolism needed for tumor survival." (PMID 38959243, 2024). "In addition, molecular features related to CAV1 gene expression indicate a potential role of CAV1 in tumor vasculature that supports altered metabolism, neovascularization, and EMT combined with suppressed immune response." (PMID 38959243, 2024). "The putative role of CAV1 in chemoresistance and a tumor-promoting TME, corroborated by molecular features, may explain this finding." (PMID 38959243, 2024). "The tumor microenvironment composition was estimated by ECOTYPER to investigate whether the composition differed between CAV1-high and CAV1-low tumors in SCAN-B GEX." (PMID 38959243, 2024).